PCDHB5 (protocadherin beta 5)
Description:
Potential calcium-dependent cell-adhesion protein. May be involved in the establishment and maintenance of specific neuronal connections in the brain.
Synonyms: DKFZp586B0217; PCDH-BETA5
Tractability: Antibody: UniProt places it where antibodies can reach, with medium confidence; UniProt predicts a signal peptide or a membrane-spanning region; its Gene Ontology location is reachable by antibodies, with medium confidence; the Human Protein Atlas places it where antibodies can reach. PROTAC: ubiquitination databases record sites on it.
Gene: Protein-coding gene on chromosome 5 (141,135,206 to 141,138,615, forward strand). Ensembl gene ENSG00000113209.
Subcellular location: Cell membrane
Subcellular location (Human Protein Atlas): Plasma membrane; Vesicles
Gene Ontology:
Molecular function: protein binding; cell adhesion molecule binding; calcium ion binding
Biological process: calcium-dependent cell-cell adhesion; cell adhesion; chemical synaptic transmission; synapse assembly; homophilic cell-cell adhesion; nervous system development
Cellular component: membrane; plasma membrane; synapse
Genetic constraint (gnomAD): Loss-of-function variants: 0 observed, 0.35 expected, observed/expected ratio (o/e) 0, 90% interval 0 to 1.86. That is too few expected variants to judge how well the gene tolerates losing a copy. Missense variants: 1,125 observed, 1,074.1 expected, observed/expected ratio (o/e) 1.05, 90% interval 1 to 1.1. Synonymous variants: 569 observed, 486.29 expected, observed/expected ratio (o/e) 1.17, 90% interval 1.09 to 1.25.
Homologues: Orthologues: chimpanzee PCDHB5 (98% identical), macaque PCDHB5 (95% identical), dog PCDHB5 (84% identical), mouse Pcdhb8 (77% identical), mouse Pcdhb10 (77% identical), rat Pcdhb8 (76% identical), mouse Pcdhb6 (76% identical), mouse Pcdhb4 (76% identical), rat Pcdhb4 (75% identical), rat Pcdhb10 (75% identical), mouse Pcdhb11 (75% identical), mouse Pcdhb12 (74% identical), and 1 more. Paralogues in human: PCDHB6 (77% identical), PCDHB4 (77% identical), PCDHB3 (76% identical), PCDHB15 (75% identical), PCDHB16 (75% identical), PCDHB14 (74% identical), PCDHB2 (74% identical), PCDHB12 (74% identical), PCDHB8 (74% identical), PCDHB13 (74% identical), PCDHB11 (74% identical), PCDHB7 (73% identical), and 49 more.
Diseases named in the same sentence as PCDHB5 in open-access papers:
PCDHB5 is named in the same sentence as 6 diseases in open-access papers, as found by Europe PMC text mining. Sharing a sentence is not in itself a finding about the gene and the disease. The quoted sentences say what the papers report.
lung carcinoma (1 paper, 2022). "Therefore, we further estimated the association between these mutations and the efficacy of immunotherapy in a published lung cancer dataset, and the results demonstrated that MUC19 and PCDHB5- mutations were related with favorable results of immunotherapy." (PMID 36389707, 2022).
cancer (2 papers, 2021 to 2023). A tumor composed of atypical neoplastic, often pleomorphic cells that invade other tissues. "Similarly, HHV-8 causes dysregulation of Notch pathways and hyper methylation of Protocadherin Beta-5 (PCDHB5), which has been identified to play a significant role in cancer of various types." (PMID 36826111, 2023).
PCDHB5 also shares sentences with these, for which no sentence is quoted: breast carcinoma (2 papers); neurological disease (1); non-small cell lung carcinoma (1); tumor (1).